ADAMTS13 (ADAM metallopeptidase with thrombospondin type 1 motif 13)
Diseases named in the same sentence as ADAMTS13 in open-access papers (continued):
Sharing a sentence is not in itself a finding about the gene and the disease.
Stroke (55 papers, 2013 to 2025). Sudden impairment of blood flow to a part of the brain due to occlusion or rupture of an artery to the brain. "It has been suggested that in the general population, ADAMTS activity, VWF: Ag, and especially the VWF: Ag/ADAMTS13 Ratio, are associated with stroke risk development independently of other factors." (PMID 40217918, 2025). "Clinical and experimental studies reveal that low ADAMTS13 plasma levels are associated with an increased risk of myocardial infarction, stroke, or arterial thrombosis in subarachnoid hemorrhage." (PMID 41009700, 2025). "Future research should focus on the role of ADAMTS13 genetic variants and stroke severity and mortality." (PMID 40217918, 2025). "A low ADAMTS13 activity remained a significant risk factor for stroke, even after adjustment for traditional cardiovascular risk factors (including age, gender, smoking status, blood pressure, diabetes, and cholesterol)." (PMID 39274365, 2024). "Increased risk for stroke in patients with iTTP in remission but with low ADAMTS13 activity was recently confirmed." (PMID 37895305, 2023). "This premise is also supported by large population-based cohort studies from the Netherlands, where lower ADAMTS13 activity has been identified as a risk factor for coronary heart disease, stroke, and all-cause and cardiovascular mortality." (PMID 37762903, 2023). "Among 36 patients with iTTP in clinical remission, patients with lower ADAMTS13 activity had higher risk for stroke." (PMID 37895305, 2023). "Subjects in the lowest quartile of normal ADAMTS13 activity had twice the risk for stroke (7.3%) as subjects in the highest quartile (3.6%)." (PMID 37895305, 2023). "ADAMTS13 activity during clinical remission has emerged as an important targetable risk factor for iTTP relapse and other outcomes including stroke and all-cause mortality." (PMID 36926315, 2023). "ADAMTS13 deficiency is a risk factor for developing myocardial infarction, stroke, cerebral malaria, and preeclampsia." (PMID 38203218, 2023). "In large population-based cohorts from the Netherlands, lower ADAMTS13 activity has emerged as a risk factor for coronary heart disease, stroke, and all cause and cardiovascular mortality." (PMID 36926315, 2023). "ADAMTS-13 activity is inversely correlated with the number of vascular risk factors across different stroke etiologies." (PMID 36703637, 2022). "Despite the increasing evidence on the role of ADAMTS-13 in stroke pathophysiology, however, less is known regarding its potential as a biomarker of stroke etiology and as an indicator of cerebrovascular risk among specific stroke causes." (PMID 36703637, 2022). "Others and we have previously demonstrated that lower ADAMTS-13 activity was associated with an unfavorable clinical course following acute stroke therapies, that is, mechanical thrombectomy and intravenous thrombolysis." (PMID 36703637, 2022). "Lower levels of ADAMTS-13 are associated with stroke, myocardial infarction, and cardiovascular mortality." (PMID 36703637, 2022). "Correlation of ADAMTS-13 activity with vascular risk scores in cohort 1, stratified by stroke etiology." (PMID 36703637, 2022). "A disintegrin and metalloprotease with a thrombospondin type 1 motif, member 13 (ADAMTS-13) has antithrombotic properties and was repeatedly implicated in the pathophysiology of stroke." (PMID 36703637, 2022). "Different authors reported the existing link between ADAMTS13 variants and stroke or other cardiovascular diseases, whereas our group was the first to describe an excess of rare ADAMTS13 variants in a small group of 94 DVT patients and 98 controls." (PMID 34662354, 2021). "In a meta-analysis that investigated the association between VWF, ADAMTS13 and cardiovascular outcomes, most of the studies found an increased risk of myocardial infarction or stroke." (PMID 34134634, 2021).
Stroke (continued). "Risk estimates for decreased ADAMTS13 activity ranged from a 0.5-fold to an 8.2-fold increased risk of myocardial infarction and ranged from a 1.7-fold to a 7.3-fold increased risk of stroke." (PMID 34134634, 2021). "Stroke can also occur after recovery from acute iTTP and is associated with reduced ADAMTS13 activity during remission." (PMID 33586004, 2021). "The importance of ADAMTS13 function is highlighted by the association of low ADAMTS13 levels with increased risk of both myocardial infarction and stroke." (PMID 33863735, 2021). "The VWF Ag:ADAMTS13 ratio has been highlighted in other thrombotic conditions with higher ratios being associated with inferior outcomes in stroke and cardiac disease." (PMID 33363289, 2021). "Accordingly, experimental stroke studies showed that ADAMTS13-deficient mice developed larger brain infarctions and worse neurologic outcomes, whereas infusion of recombinant ADAMTS13 was able to attenuate ischemic brain damage." (PMID 31921147, 2019). "Intriguingly, increased VWF activity and/or reduced ADAMTS13 activity are associated not only with higher stroke occurrence, but also with worse long-term stroke outcomes." (PMID 31921147, 2019). "It was discovered that ADAMTS13 single nucleotide variants were closely associated with pediatric stroke susceptibility." (PMID 31379722, 2019). "The enhanced activity of the GoF ADAMTS‐13 variant translates to a more pronounced protective effect in experimental stroke." (PMID 30152919, 2018). "A study involving a large cohort of patients with iTTP who presented with stroke found that smoking, hypertension, old age, and high plasma concentration of ADAMTS13 IgG may contribute to the risk of developing ischemic infarction in these patients." (PMID 40109809, 2025). "Additionally, in this study, the VWF: ADAMTS13 ratio was associated with stroke severity and mortality." (PMID 40217918, 2025). "Remission ADAMTS13 activity is also an attractive therapeutic target because of its association with stroke and other vascular diseases, and the availability and long experience with immunosuppressive agents that target anti-ADAMTS13 antibodies and can help increase ADAMTS13 activity levels." (PMID 37762903, 2023). "One of the more provocative findings from observational studies is the association of lower remission ADAMTS13 activity in iTTP survivors with a number of adverse health outcomes, including stroke, silent cerebral infarction, and a trend towards higher all-cause mortality." (PMID 37762903, 2023). "Even in healthy individuals, a slight decrease in ADAMTS13 activity (<70%) is a risk for stroke." (PMID 37240470, 2023). "The risk of stroke during clinical remission is increased nearly fivefold compared with age and sex matched control population (13.1 vs. 22.6%) and this risk is strongly associated with incomplete ADAMTS13 recovery during clinical remission." (PMID 36926315, 2023). "Additionally, it is suggested that decreased level of ADAMTS-13 is associated with stroke recurrence after remission, hence the importance of patients’ follow-up." (PMID 36709264, 2023). "In addition to traditional cardiovascular risk factors, recent data suggests that low ADAMTS13 activity is a risk factor for some of these outcomes, particularly stroke." (PMID 36926315, 2023). "In this study, we, therefore, aimed to investigate whether ADAMTS-13 is associated with stroke etiology and the burden of vascular risk factors." (PMID 36703637, 2022). "As ADAMTS13 previously has been linked to AF andischemic stroke, our findings suggest that the 1342 G-allele may be of significance.The possible association observed between the c.1342C>G SNP and clinical outcomeafter 2 years needs further investigations." (PMID 36474435, 2022). "Low-ADAMTS13 is a vascular risk factors for stroke recurrence." (PMID 33586004, 2021). "A recent study reported an association between low ADAMTS13 levels and high stroke incidence." (PMID 34276770, 2021).
Stroke (continued). "This release is mediated by ADAMTS-13, so that ADAMTS-13 deficiency is associated with occlusive diseases such as myocardial infarction and stroke, and its low activity is a predictor of unfavorable results in patients with ischemic stroke undergoing endovascular therapy." (PMID 32150898, 2020). "Also, in TTP patients who have recovered and are in remission, lower ADAMTS13 activity levels after recovery are associated with stroke." (PMID 33352066, 2020). "The VWF: ADAMTS13 ratio has a stronger correlation with the risk of stroke than either of them." (PMID 31379722, 2019). "However, they found that the VWF:ADAMTS13 ratio was significantly associated with stroke severity and modality." (PMID 31379722, 2019). "At the molecular level, ADAMTS13, one of the extracellular matrix components, in conjunction with phosphoinositide and calcium signaling pathways, plays a vital role in determining the susceptibility for stroke." (PMID 31379722, 2019). "The VWF:ADAMTS13 ratio has a strong correlation with the risk of stroke." (PMID 31379722, 2019). "In addition, a number of studies reported a significant association between low activity/ levels of ADAMTS13 and stroke." (PMID 31379722, 2019). "Importantly, correlation between ADAMTS13 activities and the incidence of stroke persisted after adjusting for common risk factors such as age, sex, diabetes and atrial fibrillation." (PMID 31379722, 2019). "We have previously shown that low activity of ADAMTS13 itself is associated with increased risk of cardiovascular disease, while the combination of VWF and ADAMTS13 appears indeed more strongly associated with stroke risk than what would be expected on the basis of the individual measurements." (PMID 29615758, 2018). "Still, low ADAMTS13 activity might be an independent risk factor for stroke occurrence as shown by a large observational case–control study in young women with stroke in which the ADAMTS13 measurements were performed in the very late phase after stroke." (PMID 29847840, 2018). "Moreover, the univariate analysis revealed that VWF:ADAMTS13 ratios were significantly associated with stroke severity (NIHSS: p = 0.048; BI: p = 0.004 and mRS: p = 0.015) and stroke modality (AIS or TIA; p = 0.023)." (PMID 28591212, 2017). "The VWF:ADAMTS13 ratio was significantly associated with stroke severity and modality." (PMID 28591212, 2017). "In addition to traditional cardiovascular risk factors, low ADAMTS13 activity during clinical remission may be a risk factor for some of these outcomes, such as stroke." (PMID 37762903, 2023). "We hypothesized that (I) ADAMTS-13 activity differs according to stroke etiology, (II) ADAMTS-13 activity is inversely associated with the number of vascular risk factors, and (III) lower ADAMTS-13 activity may reflect a higher probability for paradoxical embolism in stroke patients with PFO." (PMID 36703637, 2022). "Importantly however, unlike those with iTTP, all patients with cTTP are at significantly increased risk for transient ischemic attack (TIA) and overt stroke starting at a young age, with up to 20% lifetime incidence of stroke given potential long term ADAMTS13 deficiency." (PMID 35479064, 2022). "Therefore, screening patients free of stroke at preventive check-ups could help to identify high-risk patients, stratifying them for risk of future stroke based on their vWF levels and/or ADAMTS13 activity." (PMID 29847840, 2018). "In further sensitivity analyses, associations of VWF and ADAMTS13 with dementia were similar for Alzheimer’s disease only, and unaffected by excluding those with prevalent cardiovascular disease and censoring participants at time of myocardial infarction or stroke during follow-up." (PMID 29615758, 2018).
Stroke (continued). "While ADAMTS13 is critical in limiting thrombus formation in acute thromboinflammatory settings such as stroke or TTP, it appears to be dispensable for collateral artery and capillary growth in models of gradual perfusion recovery driven by arteriogenesis." (PMID 41009700, 2025). "Among these, three are likely monogenic causes of stroke (ELN, SCN5A, and VHL genes), two are considered risk factors (FV and ADAMTS13), two have conflicting interpretations (ACAD9 and ENG), and three are most likely benign (CBS, PMM2, and PKD1)." (PMID 40650005, 2025). "In this prospective study, the association between ADAMTS13 activity, VWF: Ag, and the VWF: Ag/ADAMTS13 Ratio and stroke outcomes was examined." (PMID 40217918, 2025). "These strata correlate with a 0% incidence of stroke in those with ADAMTS13 over 70% versus 27.6% for those with levels below 70%." (PMID 39274365, 2024). "Research has shown that patients with ADAMTS13 activity of less than 70% during clinical remission are five times more likely to have a stroke." (PMID 39125707, 2024). "Prevention of stroke and other thrombotic complications depend on the level of ADAMTS13 in the body and the level that aids in prevention of these complications has not been established." (PMID 37895305, 2023). "The same group has published two reports that show how recombinant ADAMTS13 can potentially reduce inflammation in mice suffering from stroke and myocardial ischaemia/reperfusion injury." (PMID 38203218, 2023). "In conclusion, in the long-term course after stroke due to different etiologies, ADAMTS-13 activity inversely correlates with the number of vascular risk factors." (PMID 36703637, 2022). "ADAMTS13 expression showed beneficial effects in preserving BBB in some CNS injury diseases such as stroke and intracerebral haemorrhage." (PMID 36232832, 2022). "Up to date, only a few biomarkers, such as ADAMTS13 activity, Aquaporin-4, leukocyte count, and neutrophil to lymphocyte ratio, were found to be associated with post-thrombolytic ENI in stroke." (PMID 36315566, 2022). "We enrolled two different stroke cohorts in which we determined ADAMTS-13 activity in peripheral venous blood in the long-term course after the event." (PMID 36703637, 2022). "We determined ADAMTS-13 activity in two prospectively recruited stroke cohorts in the long-term course after the event." (PMID 36703637, 2022). "ADAMTS-13 activity was lower in patients with AF-related stroke compared to patients with ESUS (p = 0.0227), which was, however, due to confounding by vascular risk factors." (PMID 36703637, 2022). "Complete deficiency in ADAMTS13 induces a prothrombotic state, which represents an important risk factor for TTP or stroke, but it is insufficient to cause TTP or stroke by itself." (PMID 34501736, 2021). "In experimental stroke models, N-Acetylcysteine, a mucolytic drug, and ADAMTS13, a vWF cleaving enzyme, have shown to effectively dissolve tPA resistant thrombi and reduce cerebral infarct size." (PMID 33732203, 2021). "In line with our results, numerous studies have reported that ADAMTS13 obviously reduced inflammation in atherosclerosis and stroke via cleaving active VWF." (PMID 32075652, 2020). "Since ADAMTS13 level varied over time after stroke process, serial blood samples will be needed to determine which timepoint was the best for predicting long-term clinical outcomes and hemorrhagic transformation." (PMID 32849241, 2020). "In animal models of ischemic stroke, the administration of recombinant ADAMTS-13 after a stroke appears to be beneficial." (PMID 33352066, 2020). "Importance of ADAMTS13 has been reported in stroke patients, wherein the VWF/ADAMTS13 ratio was a predictive of outcome and associated with an increased risk of ischemic stroke." (PMID 32731558, 2020). "Recent studies have confirmed the effect of the ADAMTS13-VWF axis on blood–brain barrier (BBB) permeability in mice with stroke and traumatic brain injury." (PMID 32075652, 2020).
Stroke (continued). "Decreased ADAMTS13 levels were previously identified in the plasma from patients with many conditions, such as systemic inflammation, stroke, and MS." (PMID 32075652, 2020). "Recently, the relationship between ADAMTS13 and ischemic stroke has become a focus of stroke research." (PMID 31379722, 2019). "Taken together, it is clear that levels of ADAMTS13, as well as levels of VWF, are associated with the risk of stroke in the general population." (PMID 31379722, 2019). "Correspondingly, ADAMTS13 deficient mice showed an increased number of thrombi containing fibrin and VWF in the brain lesions after stroke." (PMID 31921147, 2019). "Taken together, these data support the rationale that not only vWF levels, but also the vWF-modifying enzyme ADAMTS13 plays an important role in the development of first-ever stroke." (PMID 29847840, 2018). "In a murine stroke model, GoF ADAMTS‐13 restored cerebral blood flow at a lower dose than WT ADAMTS‐13, and partially retained the ability to recanalize vessels when administration was delayed by 1 h." (PMID 30152919, 2018). "As well as the treatment of stroke 41 and myocardial infarction 42, the use of recombinant ADAMTS‐13 as a replacement therapy in acquired TTP 47 and the possibility of gene therapies to overcome ADAMTS‐13 deficiency 48 are also being investigated." (PMID 27514025, 2016). "However, the SARS‐CoV2 infection's contribution to any VWF/ADAMTS13 axis imbalance and the subsequent thromboinflammatory response post‐stroke remain poorly understood." (PMID 39972966, 2025). "Similarly, genetic and functional data have been reported in pediatric patients regarding decreased ADAMTS13 and stroke development." (PMID 40217918, 2025). "Moreover, ADAMTS13 has an important role in stroke angiogenesis, by induction of vascular endothelial growth factor production." (PMID 40217918, 2025). "Similarly, in the study by Taylor and colleagues, the VWF: Ag/ADAMTS13 activity ratio at stroke presentation correlated with higher modified Rankin scale scores (p = 0.021) and NIHSS scores (p = 0.029) at follow-up." (PMID 40217918, 2025). "High vWF levels, as seen in stroke and cardiovascular disease, could also be potentially mitigated by recombinant ADAMTS13 more safely than by plasma transfusion, thus showing the potential of this protein in biomedical applications." (PMID 38396603, 2024). "It is possible, but as yet unproven, whether targeting higher levels will improve outcomes such as stroke and mortality, and optimal ADAMTS13 targets still need to be established." (PMID 36926315, 2023). "ADAMTS13 was also shown to down-regulate platelet adhesion to the exposed subendothelium and thrombus formation in injured arterioles and reduce ischemic brain injury in experimental stroke." (PMID 37240470, 2023). "Thus, we aimed to investigate ADAMTS-13 activity in two thoroughly characterized stroke cohorts with an emphasis on ESUS." (PMID 36703637, 2022). "Accordingly, future studies should further investigate the extent to which ADAMTS-13 may provide additional benefit in predicting recurrent vascular events in different stroke subtypes." (PMID 36703637, 2022). "In this course, longitudinal observation regarding vascular endpoints is also warranted to investigate whether ADAMTS-13 may serve as a predictive biomarker of stroke recurrence in patients with known and unknown etiologies." (PMID 36703637, 2022). "In the general population, most previous studies focused on the association between VWF, ADAMTS13 and non-fatal cardiovascular outcomes (myocardial infarction or stroke)." (PMID 34134634, 2021). "We also suggest that ADAMTS13 could be targeted to promote cleaving of vWF, thereby preventing thrombus formation and subsequent stroke." (PMID 33930055, 2021). "A mild decrease of ADAMTS13 (a disintegrin and metalloprotease with thrombospodin type 1 motif 13) could attribute to stroke and coronary heart disease in general population." (PMID 34819564, 2021).